PTPRD (protein tyrosine phosphatase receptor type D)
Diseases named in the same sentence as PTPRD in open-access papers (continued):
Sharing a sentence is not in itself a finding about the gene and the disease.
tumor (continued). "Third, we explored the effect of PTPRD/PTPRT mutations on TCR diversity, which was strongly associated with the anti-tumor response." (PMID 36248841, 2022). "The expression of PTPRD at 9p23 was lower in ccRCC than in normal tissue, and weakly correlated with SCNAs and tumor progression." (PMID 35677048, 2022). "As both CNTNAP2 and PTPRD analyses predated the updated WHO diffuse glioma classification, we analyzed these further in the TCGA cohort with updated tumor classification based on IDH mutation and 1p19q co-deletion." (PMID 35982066, 2022). "Studies have shown that PTPRD is frequently inactivated in various malignancies and lacks induction of tumor cell metastasis." (PMID 35047401, 2021). "In LUAD cohort, the mutation ratio of KRAS, an oncogene which leads to immune escape in the tumor microenvironment, and PTPRD, which affects the tumor proliferation, were higher than LUSC also suggests the difference immune response mechanisms." (PMID 33927719, 2021). "In our present study, detection of PTPRD phosphatase-mut took enough ctDNA as a prerequisite, which was based on higher tumor burden." (PMID 34615542, 2021). "They found that high expression of PTPRD suppressed STAT3 phosphorylation in healthy liver tissue but low expression of this protein in HCC resulted in the tumor-specific STAT3 activation." (PMID 31547152, 2019). "Only in 1 cell was there found a gain of the chromosomal region 9p24.3–9p23, where PTPRD is located, which has been reported to act like a tumor suppressor gene in NB, in addition to other genes, indicated to be related to cancer (i.e., JAK2, RLN2, TYRP1)." (PMID 30791380, 2019). "PTPRT/PTPRD dephosphorylate various signaling molecules, stabilize cell-cell adhesions and inhibit tumor migration." (PMID 30200630, 2018). "Tumor suppressive properties of PTPRD were reported in several human tumors such as glioblastoma multiforme, melanoma, gastric adenocarcinoma, lung cancer, neuroblastoma, and laryngeal squamous cell carcinoma." (PMID 29558404, 2018). "In particular mutations in ERBB2, PTPRD, PTPRT, AURKB correlated with at least one of the clinical-pathological parameters under analysis such as node status (N), stage, tumor size (T) and/or presence of metastasis (M1)." (PMID 29844865, 2018). "PTPRD has been characterized as a tumor suppressor gene in MM and a homozygous deletion in PTPRD encoding locus is known to modulate phosphorylation of STAT3 that promotes IL6 signaling." (PMID 30134812, 2018). "Inactivating mechanisms include homozygous or heterozygous deletion, microsatellite alterations, and epigenetic silencing, suggesting that PTPRD is a tumor-suppressor gene." (PMID 29228728, 2017). "Tumor volume measurements showed that PTPRD downregulation significantly promoted xenograft formation and growth." (PMID 29228728, 2017). "Varying the permutation test to control for tumor stage or histological subtype instead of CIN also found PTPRD deletion as the event most correlated with East/West status." (PMID 28426752, 2017). "Microarray analyses revealed that PTPRD was upregulated in lung metastases samples compared to tumor samples." (PMID 26474282, 2015). "PTPRD is one of the most commonly mutated PTPR family members in HNSCC, and PTPRD has been reported to function as a tumor suppressor in this malignancy." (PMID 26267899, 2015). "Reduced expression of PTPRD was significantly correlated with tumor size (P = 0.003), depth of tumor infiltration (T stage, P = 0.004), and TNM stage (P<0.001)." (PMID 25412184, 2014). "The PTPRD expression level was significantly lower in 32 (76.19%) tumor-bearing tissues compared with the adjacent non-tumor tissues (P = 0.0138)." (PMID 25412184, 2014). "Two mutations were identified in her tumor sample collected between the two lines of treatment, a GRB10 Q107stop mutation and a PTPRD W775 stop mutation." (PMID 25119929, 2014).
tumor (continued). "Statistical analysis revealed that reduced PTPRD expression was significantly associated with T stage (P = 0.004), TNM stage (P<0.001) and tumor size (P = 0.003)." (PMID 25412184, 2014). "As for genomic loss, 9p21.3 (CDKN2A), 9p23-p24.1 (PTPRD) and 13q14.2 (RB1) were significantly less frequently deleted in ALK fusion-positive tumours." (PMID 23289484, 2013). "The identification of AURKA as a novel target of PTPRD mediated dephosphorylation adds to a growing list of substrates for this tumor suppressor." (PMID 22305495, 2012). "Lower than median PTPRD mRNA levels were significantly associated with both poor relapse free and overall patient survival, consistent with PTPRD having a tumor suppressor function." (PMID 22305495, 2012). "Additional tumor suppressors, including GPC5 and PTPRD, also harbored SIR-associated mutations." (PMID 41153425, 2025). "Using a tissue microarray, abundant PTPRD expression in low- and high-grade EC tumours is noted." (PMID 38339334, 2024). "The EC TMAs revealed abundant PTPRD expression in both low- and high-grade tumours." (PMID 38339334, 2024). "In terms of liquid biopsies, future studies are needed to confirm whether circulating tumour cells also express PTPRD, and if its expression is altered during treatments." (PMID 38339334, 2024). "Moreover, our analysis of PTPRD gene methylation levels using TCGA data revealed a substantial increase in methylation within the PTPRD promoter region of tumor tissues." (PMID 39639918, 2024). "The third one is loss&CN-LOH on 9p (hotspot #11) that may target several tumor suppressors, among them SMARCA2, NFIB and PTPRD." (PMID 38473323, 2024). "The mutation of PTPRD may influence CD4+ T cell infiltration via its phosphatase activity, and promote the occurrence of “hot” TME with enhanced anti-tumor immunity in advanced NSCLC patients." (PMID 37602864, 2023). "It is thus possible that PTPRD plays a tumor suppressor role in preventing metastatic CSCC." (PMID 35982973, 2022). "In the context of cancer disease, PTPRD is absent or inactive in a variety of human tumor types, playing a tumor suppressor role linked with the downregulation of STAT3 activity." (PMID 34957126, 2021). "Receptor-type tyrosine-protein phosphatase delta (PTPRD) is frequently found to be inactivated by epigenetic modification in a variety of tumors, suggesting that it may have tumor suppressive effects." (PMID 35126454, 2021). "Moreover, expression of some PTP tumor suppressors, such as PTPRD, PTPRO, PTPN12, PTPN13 and DUSP1, is reduced due to epigenetic silencing." (PMID 29558404, 2018). "Although no copy number loss was observed for PTPRT, PTPRD heterozygous deletions occurred in four patients, in whom only one gene copy was observed in the tumor tissue." (PMID 30200630, 2018). "In addition to promoter hypermethylation, deletion and mutation of PTPRD gene were also identified in HCC cell lines and tumor tissues." (PMID 29558404, 2018). "PTPRD has been reported to serve as a tumor suppressor in human cancer." (PMID 26267899, 2015). "Collectively, these results suggest that PTPRD mutations inactivate the tumor suppressive function of PTPRD irrespective of their localization throughout the gene, leading to increased growth/proliferation in HNSCC cells." (PMID 26267899, 2015). "NGS performed on a tumor sample from the chest wall biopsy obtained at the time of diagnosis revealed PIK3CA mutation H1047R, CTNNB1 mutation S37C, and protein tyrosine phosphatase delta (PTPRD) mutation S1845fs*2." (PMID 24931142, 2014). "The tumor unexpectedly contained a BRAF V600E mutation, CDKN2A loss and PTPRD S1845fs*2 mutation." (PMID 25563358, 2014).
tumor (continued). "Taken together, these results demonstrated that PTPRD might serve as a tumor suppressor in a broad spectrum of human tumor types." (PMID 25412184, 2014). "Recently, PTPRD has been proposed to function as a tumor suppressor gene." (PMID 25412184, 2014). "Taken together, our research suggested that PTPRD was a candidate tumor suppressor in GC." (PMID 25412184, 2014). "Crizotinib was added to this regimen; however, he had disease progression on this chemotherapy and was referred to our service where tumor sequencing (lung metastases) revealed MET amplification, PI3KCA V344G mutation, CCNE1 amplification, and PTPRD S1845fs*2 mutation." (PMID 25126591, 2014). "These researches suggested that PTPRD might be one of a select group of tumor suppressor genes that are inactivated in a wide range of common human tumor types." (PMID 25412184, 2014). "The alterations found in this tumor were the BRAFV600E mutation, CDKN2A loss and PTPRD S1845fs*2." (PMID 25563358, 2014). "Protein tyrosine phosphatase delta (PTPRD) is a tumor suppressor that inhibits STAT3 activation." (PMID 23800680, 2013). "PTPRD undergoes a high frequency of hemizygous/homozygous deletions in multiple forms of cancer, which are often intragenic in nature, indicating a potential tumor suppressor function." (PMID 22305495, 2012). "Additionally, PTPRD/PTPRT mutations were strongly associated with a higher TMB, MSI score, TCR score, higher levels of immune cell infiltration, and enriched immune-related signatures, indicating an enhanced level of anti-tumor immunity in PTPRD/PTPRT mutant cancer patients." (PMID 36248841, 2022). "Mechanistically, PTPRD/PTPRT mutations are strongly associated with high TMB, high MSI score, and an enhanced anti-tumor microenvironment, thus PTPRD/PTPRT mutations may be a promising biomarker for the prediction of the ICI treatment response in several cancers." (PMID 36248841, 2022). "In addition, low expression of PTPRD was significantly correlated with tumor size (P = 0.003), depth of tumor infiltration (T stage, P = 0.004), and TNM stage (P<0.001), but not with age, gender, local lymph node metastasis (N stage), or distant metastasis (M stage)." (PMID 25412184, 2014). "PTPRD, a member of the PTP family, has been reported to act as a tumor suppressor gene and plays a crucial role in controlling numerous cellular processes, including cell proliferation, apoptosis, survival and motility." (PMID 36660927, 2023). "To further study the clinical significance of PTPRD and CNTNAP2 in diffuse gliomas with the current WHO tumor classification, we analyzed TCGA diffuse glioma data for chromosomal rearrangements, CNAs, DNA methylation, and RNA expression levels of these genes." (PMID 35982066, 2022). "In sample P9, a GG 3 tumor described as PI-RAD5 region in MRI, OGM found deletion of chr9p23 (start position: 10,018,386; end position: 10,022,066) affecting PTPRD gene." (PMID 36209207, 2022). "Most MHC I molecules, including HLA-A, HLA-C, HLA-E, HLA-F, TAP1, TAP2, and TAPBP (all P < 0.05), were upregulated in PTPRD/PTPRT mutant patients, indicating enhanced anti-tumor immunity in PTPRD/PTPRT mutant patients." (PMID 36248841, 2022). "Among these, ERBB2, PTPRD, PTPRT, AURKB also correlated with node status, stage, tumor size and/or presence of metastasis." (PMID 29844865, 2018). "Among the eight down-regulated genes, one is an oncogene (NEAT1), six are tumor-suppressor genes (ASS1, PTPRD, ISG15, TGFBI, SELENBP1, MEG3) and one gene serves as both an oncogene and tumor-suppressor gene (CDH17)." (PMID 30563222, 2018). "Tumor volume was strongly correlated with the CN amplifications of subclone 1–ERBB4, LRP1B, PTPRD, and EPHA5 CN all exhibited r ∈ [0.76,0.79] and p-value ∈ [4.8e-4, 9.4e-4]." (PMID 30560892, 2018). "Tumor change from baseline and the genetic alteration status for PTPRT/PTPRD are displayed in a waterfall plot." (PMID 30200630, 2018).
tumor (continued). "Deletions at the level of chromosome region 9p determine loss of heterozygosity at the level of the loci of two important tumor suppressor genes such as CDKN2A and PTPRD." (PMID 30060526, 2018). "The present study showed that PTPRD knockdown significantly increased STAT3 activation in vitro, and promoted tumorigenesis in mice characterized also by high pSTAT3 expression in tumor cells in vivo." (PMID 29228728, 2017). "In addition, elevated M1 infiltration and decreased M2 infiltration levels were observed in PTPRD/PTPRT mutant cancer patients, which can enhance anti-tumor immunity." (PMID 36248841, 2022). "PTPRD has also other relevant targets, such as aurora kinase A (AURKA), which may also mediate its tumor suppressive functions." (PMID 35982066, 2022). "As for the PTPRD gene, there were no reports about this gene in the tumor immunity area yet, but the PTPRD gene was involved in the JAK/STAT signaling which was found to be associated with tumor immunotherapy." (PMID 36120536, 2022). "In total, recurrent (>3) MEI were observed in 329 protein-coding genes of which 28 genes are annotated in the Cancer Gene Consensus with either oncogenic (ALK1, ERBB4, TSHR, PREX2, CTNNA2, CTNND2) or tumour suppression roles (EBF1, LRP1B, PTPRD, GPC5, ROBO2, PTPRT)." (PMID 35301290, 2022). "Furthermore, the expression levels of CXCL9, CXCL10, CXCL11, and their receptor CXCR3, which perform anti-tumor roles in ICI treatment, were found to have increased in PTPRD/PTPRT mutant cancer patients." (PMID 36248841, 2022). "Conversely, we found the previously identified PCa driver gene LRP1B (12/17) and new candidate genes TTC28 (16/27), CADM2 (12/16), LSAMP (11/16), EYS (16/18), PTPRD (12/18), PACRG (5/6) and PDE4D (12/17) to be predominately interrupted in tumours from African patients." (PMID 36045381, 2022). "In this study, the further enrichment of immune signatures, including CD8+ T cells, Tfh, B cells, DCs, cytotoxic activity, and pro-inflammation, were observed in PTPRD/PTPRT mutant cancers, indicated of the formation of an enhanced anti-tumor immune microenvironment." (PMID 36248841, 2022). "Non-responsive tumor portions had consistently complete loss of ANKRD28 and PTPRD expression unlike their responsive counterparts." (PMID 36132155, 2022). "These might include genes with tumor suppressive properties, such as CDKN2B (9p21), SH3GL2 (9p22), PTPRD (9p23), and DOCK8 (9p24)." (PMID 27835607, 2016). "The disparity between our present findings and previous reports of PTPRD promoter methylation in HNSCC is likely due to the prior lack of comparison between tumor and normal tissue." (PMID 26267899, 2015). "Also, changes in tumour suppressor gene-related regions, such as 9p21.3 (CDKN2A) 9p23-24.1 (PTPRD), 13q14.2 (RB1), were significantly fewer in tumours with ALK fusion." (PMID 23289484, 2013). "It was also reported that PTPRD expression was found to be down-regulated or even completely absent in human HCC cell lines and tumor tissues." (PMID 29558404, 2018). "A more detailed analysis of these mechanisms next revealed that the PTPRD promoter is not hypermethylated in HNSCC relative to organ-matched normal tissue, a finding we validated in an independent cohort of HNSCC tumor and matched normal pairs by methylation-specific PCR." (PMID 26267899, 2015). "Importantly, we also observed PTPRD promoter methylation in five paired normal oral mucosa samples from these HNSCC patients, further suggesting that the PTPRD methylation observed in HNSCC is not tumor-specific." (PMID 26267899, 2015).
cancer (86 papers, 2010 to 2025). A tumor composed of atypical neoplastic, often pleomorphic cells that invade other tissues. "Our analysis identified numerous SIR-associated mutations in oncogenes (e.g., MECOM, NFATC2) and tumor suppressor genes (e.g., LRP1B, PTPRD), as well as in cancer-associated lncRNAs (e.g., MALAT1, NEAT1)." (PMID 41153425, 2025). "The pan-cancer frequency of PTPRD or PTPRT (PTPRT/PTPRD) mutations was analyzed using data from TCGA." (PMID 36248841, 2022). "Third, further analyses need to be conducted in the future due to the small sample sizes of PTPRD/PTPRT mutation patients of certain types of cancers, such as GBM, RCC, and HNSC, included in this study." (PMID 36248841, 2022). "Fifth, the frequency of four DNA mismatch repair (MMR) gene mutations were higher in the PTPRD/PTPRT mutant cancer patients, compared with WT patients (all P < 0.001)." (PMID 36248841, 2022). "In the second dataset, LUSC, PIK3CA (46.5%), EGFR (7%), PDE4DIP (6.6%), KRAS (4.4%), and RELN (4.4%) were labeled with copy number gain, while CDKN2A (27.9%), LRP1B (17.4%), PTEN (9.8%), and PTPRD (9%) appeared to be the cancer genes with copy number loss." (PMID 35330454, 2022). "PTPRD polymorphisms have been associated with susceptibilities to cancer, notably renal cell carcinoma (rs2279776; p.G1418=) and endometrial cancer (rs2475335; intron variant)." (PMID 36755664, 2022). "Continuing our analysis, PTPRD mutation status was also associated with improved overall survival in the pan-cancer cohort using the Kaplan Meier method." (PMID 35798829, 2022). "In TCGA pan-cancer cohort, survival analysis showed that the OS was worse in patients with PTPRD/PTPRT mutations than in the WT (mOS, 65.52 vs 81.11 months, HR = 1.119, 95%CI: 1.018-1.228; P = 0.014)." (PMID 36248841, 2022). "For example, DDX46 and PTPRD have been associated with several types of cancer in various studies, but in our study only a measure of intolerance against loss of function mutations provided by gnomAD indicated an involvement in core biological processes." (PMID 34605899, 2022). "The TCGA pan-cancer dataset was analyzed to explore the correlation between PTPRD/PTPRT mutations and immune signatures." (PMID 36248841, 2022). "The lollipop plot depicted the pan-cancer distribution of different types of PTPRD/PTPRT mutations, with missense mutations being the most common subtype." (PMID 36248841, 2022). "This study demonstrated that PTPRD/PTPRT mutations can be a good predictive biomarker for the efficacy of ICI treatment across multiple cancers." (PMID 36248841, 2022). "Other protein phosphatases mutated in cancer, e.g., PTPRD, also negatively regulate STAT3 activation." (PMID 31844068, 2019). "Identification of the exact regulatory mechanism underlying the effects of metformin on PTPRD expression would provide further support for its use in cancer therapy." (PMID 31805999, 2019). "It has previously been shown that phosphorylated STAT3 (p-STAT3) is a substrate of PTPRD and that cancer-specific mutations in PTPRD abrogate the ability of the phosphatase to dephosphorylate STAT3." (PMID 31805999, 2019). "Loss of PTPRD expression was observed in highly invasive cancers and correlated with patient survival." (PMID 29755661, 2018). "In normal cells, this feedback circuit contributes to the maintenance of cell homeostasis; in contrast, in cancer cells loss of PTPRD expression or function leads to STAT3 overactivation and promotion of tumorigenesis." (PMID 29228728, 2017). "PTPRD encodes the protein tyrosine phosphatase receptor type D and is frequently inactivated across many human cancers." (PMID 25138050, 2014). "Additionally, our analysis revealed longer PFS in patients with high NK cells, interferons, and RB1 mutations, whereas high cancer-associated fibroblasts levels and mutations in the mTOR signaling pathway and PTPRD were indicators of shorter PFS." (PMID 39962074, 2025).